PLAC8 (placenta associated 8)
Diseases named in the same sentence as PLAC8 in open-access papers (continued):
Sharing a sentence is not in itself a finding about the gene and the disease.
infection (12 papers, 2013 to 2025). The state of being infected such as from the introduction of a foreign agent such as serum, vaccine, antigenic substance or organism. "In these studies, loss‐of‐function of SPNS1 and PLAC8 using different CRISPR vectors significantly reduced the infection susceptibility of Calu1ACE2 cells to S‐typed lentiviruses." (PMID 36124427, 2022). "By contrast, all the other cell lines displayed modest basal levels of infection, ranging from 2 to 20% positive cells, that were boosted dramatically upon PLAC8 overexpression (up to 38‐fold change compared with GFP overexpression for H226ACE2 cells)." (PMID 36124427, 2022). "We recently showed that clearance of C. muridarum from the genital tracts of C57BL/6 mice during 8 weeks following infection was dependent on having either a functional iNOS or Plac8 mechanism." (PMID 23691028, 2013). "Furthermore, a genome-wide CRISPR knockout screen identified PLAC8 as an essential factor for infection with a different coronavirus, swine acute diarrhea syndrome coronavirus." (PMID 40532694, 2025). "We selected the four cell lines that showed the strongest induction in infection efficiency upon PLAC8 overexpression, as well as Calu1ACE2 and H1299 ACE2 cells, and challenged them with SARS‐CoV‐2 for 24 h, after which cells were fixed and stained for protein N using immunofluorescence." (PMID 36124427, 2022). "In summary, we have demonstrated herein that SPNS1 and PLAC8 are host factors necessary for SARS‐CoV‐2 entry and that PLAC8 is a limiting factor that enables human pulmonary cells for infection." (PMID 36124427, 2022). "These genes contribute to the regulation of iron metabolism (FTH1), modification of proteins in response to infection (HERC5), presentation of antigens to the immune system (MAMU-AG), control of apoptotic pathways (IFI6 and PLAC8), and direct antiviral activities." (PMID 40742121, 2025). "Notably, all PLAC8 and SPNS1 KO cell lines showed a dramatic reduction in infection efficiency using S‐typed lentiviruses, reaching higher fold‐change levels than any positive control (except for ACE2‐KO)." (PMID 36124427, 2022). "By contrast, Calu1ACE2 cells, which have already high endogenous levels of PLAC8, did not experience any increase in infection efficiency upon PLAC8 overexpression." (PMID 36124427, 2022). "However, both iNOS-dependent (nitric oxide) and Plac8-dependent mechanisms were required for sterilizing immunity as viable C. muridarum could be recovered from genital tracts of Plac8 knockout mice that had previously cleared a primary infection by delayed treatment with MLA." (PMID 23691028, 2013). "In fact, the infection efficiency correlated much better with PLAC8 than with ACE2 levels, since, for example, H358 cells, which have the highest ACE2 levels but no detectable PLAC8, display much lower infection efficiencies than H1299ACE2 cells, which exhibit low ACE2 and high PLAC8 levels." (PMID 36124427, 2022). "Notably, Calu1ACE2, the cell line that expresses the highest PLAC8 levels, did not experience any infection change, while H1299ACE2 cells, which exhibits moderate levels of this protein, showed only a modest increase in infectability upon PLAC8 overexpression." (PMID 36124427, 2022). "Our finding that infection with VSVG‐typed lentiviruses, which release their genome in the early endosome, is not affected by PLAC8 loss‐of‐function would support this hypothesis." (PMID 36124427, 2022). "Notably, Calu1ACE2 and H1299ACE2 cell lines showed the highest levels of infection with S‐typed lentiviruses, while ACE2 overexpression did not change protein levels of PLAC8 or SPNS1 in any cell line." (PMID 36124427, 2022).
bacterial infections (1 paper, 2022). "High expression of SPC24, NES, LOC116828075, CLSTN3, and PLAC8 was observed in the SPC24 cells of C. carbonaria, which were enriched in pathways involved in viral and bacterial infections, disease, and leukocyte transendothelial migration." (PMID 36552787, 2022).
immune dysfunction (1 paper, 2023). "TIDE analysis revealed that PLAC8 seemed to be associated with immune dysfunction yet unrelated to the TIDE score and immune exclusion." (PMID 38023190, 2023).
PLAC8 also shares sentences with these, for which no sentence is quoted: type 2 diabetes (2 papers); Arthritis (1); autoimmune disease (1); cardiovascular disease (1); chorioamnionitis (1); choriocarcinoma (1); dermatomyositis (1); fibrosis (1); fungal infections (1); heart failure (1); inflammation (1); ischemia (1); lymph node metastasis (1); myocardial ischemia (1); neuropathic pain (1); placental disorders (1); pneumonia (1); polymyositis (1); renal cell carcinoma (1); seminoma (1); septic shock (1); Sjögren syndrome (1); smallpox (1); synovitis (1); systemic inflammatory response syndrome (1); systemic lupus erythematosus (1).